TRIM52 (tripartite motif containing 52)
Description:
E3 ubiquitin-protein ligase. Positively regulates the NF-kappa-B signaling pathway. (Microbial infection) Exhibits antiviral activity against Japanese encephalitis virus (JEV). Ubiquitinates the viral non-structural protein 2 (NS2A) and targets it for proteasome-mediated degradation.
Synonyms: RNF102
Tractability: PROTAC: UniProt records ubiquitination sites on it; ubiquitination databases record sites on it.
Gene: Protein-coding gene on chromosome 5 (181,254,077 to 181,262,068, reverse strand). Ensembl gene ENSG00000183718.
Subcellular location: Cytoplasm; Cytoplasm, cytosol; Nucleus
Subcellular location (Human Protein Atlas): Nucleoli; Intermediate filaments
Gene Ontology:
Molecular function: transcription coactivator activity; ubiquitin protein ligase activity; zinc ion binding
Biological process: defense response to virus; positive regulation of canonical NF-kappaB signal transduction; protein autoubiquitination; protein ubiquitination; innate immune response; positive regulation of DNA-templated transcription; positive regulation of signal transduction
Cellular component: cytoplasm; cytosol; nucleus
Genetic constraint (gnomAD): Loss-of-function variants: 26 observed, 32.58 expected, observed/expected ratio (o/e) 0.8, 90% interval 0.58 to 1.11. The upper end of that interval is the gene's LOEUF score, 1.11, which puts it in group 4 of 6, group 1 being the genes least tolerant of losing a copy. Missense variants: 349 observed, 374.55 expected, observed/expected ratio (o/e) 0.93, 90% interval 0.85 to 1.02. Synonymous variants: 122 observed, 135.47 expected, observed/expected ratio (o/e) 0.9, 90% interval 0.78 to 1.05.
Homologues: Orthologues: macaque TRIM52 (89% identical), chimpanzee TRIM52 (87% identical), pig TRIM52 (76% identical), dog TRIM52 (72% identical), mouse Trim52 (37% identical), rat Trim52 (37% identical), zebrafish si:dkey-29p10.4 (14% identical). Paralogues in human: TRIM41 (63% identical), TRIM17 (23% identical), TRIM39 (22% identical), TRIM27 (22% identical), TRIM7 (22% identical), TRIM21 (21% identical), TRIM11 (20% identical), TRIM31 (20% identical), TRIM4 (20% identical), TRIM60 (20% identical), TRIM10 (20% identical), TRIM58 (20% identical), and 68 more.
Diseases named in the same sentence as TRIM52 in open-access papers:
TRIM52 is named in the same sentence as 18 diseases in open-access papers, as found by Europe PMC text mining. Sharing a sentence is not in itself a finding about the gene and the disease. The quoted sentences say what the papers report.
hepatocellular carcinoma (4 papers, 2018 to 2025). A malignant tumor that arises from hepatocytes. "TRIM52 is upregulated in hepatitis B virus‐associated hepatocellular carcinoma, and the upregulation of HBV X protein induces the activation of NF‐κB signalling to increase the expression of TRIM52 in HepG2 cells, which in turn promotes the proliferation of HepG2 cells." (PMID 38520211, 2024). "For instance, TRIM52, TRIM37, and TRIM47 have been linked to ovarian cancer invasion, while other members, such as TRIM37 in hepatocellular carcinoma and TRIM24 in colorectal cancer, are known to facilitate metastasis in other cancer types." (PMID 39937005, 2025). "Recently, the oncogenic role of TRIM52 has been described in hepatocellular carcinoma (HCC)." (PMID 30918473, 2019). "The up-regulation and oncogenic roles of TRIM52 have been reported in hepatocellular carcinoma." (PMID 30918473, 2019).
ovarian carcinoma (4 papers, 2018 to 2025). A malignant neoplasm originating from the surface ovarian epithelium. "It further suggested that NF-kB signal pathway involved the mechanism associated with TRIM52-mediated regulation in ovarian cancer development." (PMID 30185771, 2018). "It indicated that TRIM52 played an oncogenic role in ovarian cancer and was linked to tumor growth and development." (PMID 30185771, 2018). "Our study supported that TRIM52 acted as a positive regulator of tumorigenesis associated with ovarian cancer development via the activiation of the NF-kB signal pathway." (PMID 30185771, 2018). "The results implied that TRIM52 was closely associated with ovarian cancer development." (PMID 30185771, 2018). "Our data strongly suggested that TRIM52 plays an oncogenic role in ovarian cancer development associated with the NF-kB signal pathway and may be a potential target for cancer therapy." (PMID 30185771, 2018). "Compared to normal tissue, there is increased TRIM52 expression in ovarian cancer cells after the phosphorylation of IKKB and p65 with NF-κB activation." (PMID 36531159, 2022). "Activation of the NF-κB pathway is related to the regulation of ovarian cancer mediated by TRIM52 (Tripartite Motif 52), which acts as a pro-cancer factor in ovarian cancer." (PMID 33061854, 2020). "To explore the role of TRIM52 in tumorigenesis in ovarian cancer, we performed the present study by knocking down TRIM52 in high-expressing TRIM52 SKOV3 and CAOV3 cells and overexpressing TRIM52 in low-expression TRIM52 HO8910 cells." (PMID 30185771, 2018). "It further indicated that knockdown of TRIM52 inhibited ovarian cancer cell invasion, migration, and proliferation, but promoted cell apoptosis." (PMID 30185771, 2018). "In summary, our study confirmed that TRIM52 mRNA and protein expressions increased in ovarian cancer compared with normal ovarian tissue." (PMID 30185771, 2018). "It was strongly suggested that TRIM52 induced the activation of NF-kB signal pathway in ovarian cancer." (PMID 30185771, 2018). "The results suggested that TRIM52 overexpression promoted ovarian cancer cell invasion, migration, and proliferation, but inhibited cell apoptosis." (PMID 30185771, 2018). "Additional ZVAD experiments reduced the risk of spontaneous cells apoptosis mediated by knocking down TRIM52 and further verified the effectors of TRIM52 in promoting ovarian cancer cells invasion, migration, and proliferation." (PMID 30185771, 2018). "Tissue microarray (TMA), containing 192 ovarian cancer cases and eight normal ovary cases, was employed to evaluate TRIM52 expression." (PMID 30185771, 2018). "The purpose of this study was to explore TRIM52's role in the tumorigenesis and its potentially involved molecular mechanism in ovarian cancer." (PMID 30185771, 2018). "The purpose of the study was to explore TRIM52's role in tumorigenesis and its potential molecular mechanism in ovarian cancer." (PMID 30185771, 2018). "It suggested that knockdown of TRIM52 downregulated the ability of ovarian cancer cell invasion and migration." (PMID 30185771, 2018). "GESA confirmed that TRIM52 expression positively correlated with gene signatures involved in ovarian cancer metastasis pathway." (PMID 30185771, 2018). "In the study, we analyzed the expression of TRIM52 in ovarian cancer and its effects on ovarian tumor growth and progression." (PMID 30185771, 2018). "To identify whether NF-kB pathway was involved in TRIM52-mediated regulation in ovarian cancer development, we observed the activity of the NF-kB signal pathway." (PMID 30185771, 2018). "Moreover, our results strongly supported that the NF-kB pathway was activated by the overexpression of TRIM52 via classical activating pathway and involved in the TRIM52-mediated regulation of tumorigenesis in ovarian cancer." (PMID 30185771, 2018). "In the study, we firstly analyzed the TRIM52 expression in ovarian cancer tissue." (PMID 30185771, 2018).
ovarian carcinoma (continued). "This study provides the first evidence that TRIM52 may play an oncogenic role in ovarian cancer to promote cell invasion, migration, proliferation, but inhibit cell apoptosis." (PMID 30185771, 2018). "It indicated that MMP9, Bcl2, and caspase 3 may play roles on TRIM52-mediated regulation in ovarian cancer cells invasion, migration, and apoptosis." (PMID 30185771, 2018). "The study demonstrated that knockdown of TRIM52 in SKOV3 and CAOV3 cells inhibited ovarian cancer cell invasion, migration, and proliferation, and induced cell apoptosis." (PMID 30185771, 2018). "Absence of TRIM52 resulted in decreased ovarian cancer growth and increased apoptosis through decreasing levels of NF-κB." (PMID 36531159, 2022). "TRIM52 mRNA levels detected by qPCR were higher in ovarian cancer tissue than in paired noncancerous tissue." (PMID 30185771, 2018).
colorectal cancer (3 papers, 2019 to 2025). A primary or metastatic malignant neoplasm that affects the colon or rectum. "For example, TRIM32 positively regulates p-STAT3 levels in lung cancer, and TRIM52 promotes SHP2 ubiquitination, consequently inactivating STAT3 signaling in colorectal cancer." (PMID 36288633, 2022).
glioblastoma (2 papers, 2018 to 2019). The most malignant astrocytic tumor (WHO grade IV). "Subsequent analysis of protein lysates of several patient-derived glioblastoma lines, and human stem cell-derived cerebral organoids, demonstrated that TRIM52 protein was expressed in ten out of thirteen analyzed samples, albeit at varying relative levels." (PMID 29568378, 2018). "Also, over-expression of TRIM28 is associated with poor outcome in GM patients, while TRIM52 controls cell cycle with a reduced proliferation speed and a compromised cycle progression in U87MG and A172 glioblastoma (GBM) cell lines." (PMID 31137886, 2019). "Since the two cell lines in which TRIM52 ablation caused a growth disadvantage (U87MG and A172) are both of glioblastoma origin, we addressed whether TRIM52 knockdown affects cell migration using a trans-well assay." (PMID 29568378, 2018). "It is noteworthy that of the tested cell lines, the two with a proliferation defect in TRIM52-ablated cells are of glioblastoma origin, indicating TRIM52 may regulate proliferation in a genetic context that is glioma-, or brain-specific." (PMID 29568378, 2018). "Hence, it will be of interest to test whether ablation of e.g. mouse Trim52 affects glioblastoma cell proliferation." (PMID 29568378, 2018). "In conclusion, the data in this study show that TRIM52 expression is required for optimal cell cycle progression in U87MG and A172 glioblastoma cell lines, whereas it is dispensable for optimal growth of various other tested cancer cells lines." (PMID 29568378, 2018). "Here we specifically showed that TRIM52 provides a fitness advantage in two glioblastoma cell lines, but not in several other cancer cell lines." (PMID 29568378, 2018).
colon cancer (1 paper, 2019). "TRIM52 protein expression was measured in 5 colon cancer cell lines and normal human intestinal crypt cells (HIEC)." (PMID 30918473, 2019).
inflammatory bowel disease (1 paper, 2026). A spectrum of small and large bowel inflammatory diseases of unknown etiology. "TRIM52, a newly characterised family member, has attracted interest for its role in regulating inflammation, and emerging evidence links TRIM52 to inflammatory bowel disease, cancer, and sepsis." (PMID 41510686, 2026).
liver fibrosis (1 paper, 2024). "Enhancing PPM1A expression by targeting TRIM52 is a promising strategy to block liver fibrosis." (PMID 39199424, 2024).
periodontitis (1 paper, 2020). An acute or chronic inflammatory process that affects the tissues that surround and support the teeth. "In order to further determine the signaling pathway involved in TRIM52-mediated progression of periodontitis, we transfected HPDLCs with si-TRIM52 or si-NC, and then exposed them to LPS or PBS." (PMID 32735017, 2020). "Mechanically, knockdown of TRIM52 could mitigate LPS-induced inflammatory injury in periodontitis through TLR4/NF-κB signaling." (PMID 32735017, 2020). "Targeting TRIM52 may become an attractive strategy for the treatment of inflammatory diseases, including periodontitis." (PMID 32735017, 2020). "However, the function and mechanisms of TRIM52 in lipopolysaccharide (LPS)-induced inflammatory injury of human periodontal ligament cells (HPDLCs) in periodontitis remain undefined." (PMID 32735017, 2020). "Moreover, little is known about the role of TRIM52 in the development of periodontitis." (PMID 32735017, 2020). "Taken together, knockdown of TRIM52 mitigated LPS-induced inflammatory injury via the TLR4/NF-κB signaling pathway, providing an effective therapeutic target for periodontitis." (PMID 32735017, 2020). "Moreover, TRIM52 knockdown could mitigate LPS-induced elevation of TLR4 expression, revealing that TLR4 is involved in the impact of TRIM52 on LPS-induced inflammatory injury during periodontitis." (PMID 32735017, 2020).
prostate carcinoma (1 paper, 2018). A carcinoma that arises from epithelial cells of the prostate gland.
cancer (11 papers, 2018 to 2026). A tumor composed of atypical neoplastic, often pleomorphic cells that invade other tissues. "Recently, several studies have associated TRIM52 with the progression of human cancers." (PMID 38520211, 2024). "Consistent with a fitness-promoting function, TRIM52 is upregulated in various cancers, prompting us to investigate its regulatory pathways." (PMID 40274822, 2025). "Other genes like HNRNPA0, DCAF7, and TRIM52 functioned in diverse ways including abnormal changes in alternative splicing or activation of canonical signal pathways in relation with cancer progression." (PMID 33134164, 2020). "Unexpectedly, we recently found that TRIM52 ablation is detrimental for cell cycle progression and thus proliferation in certain human cancer cell lines in cell culture and mouse xenograft models, without affecting cell viability." (PMID 31133683, 2019). "Together, these data show that TRIM52 knockdown reduces growth fitness in some cancer cell lines, and thus indicate that TRIM52 expression provides a fitness advantage in a cell-context dependent manner." (PMID 29568378, 2018). "Taken together, these data show that TRIM52 is required for efficient tumor formation and cancer cell proliferation in a U87MG xenograft model." (PMID 29568378, 2018). "In the current study, we tested the specific hypothesis that TRIM52 is important for cancer cell fitness in a context-specific manner." (PMID 29568378, 2018). "Currently it remains unclear i) how TRIM52 influences cell cycle progression at a molecular level, and ii) whether TRIM52 plays a role in non-cancer cells." (PMID 29568378, 2018). "Together, these data suggest that proper expression of the TRIM52 gene could be required for efficient proliferation or viability only in certain genetic cancer cell backgrounds." (PMID 29568378, 2018). "Thus, while there is a strengthening notion that TRIM52 has cell essential proliferative functions –possibly explaining why it has been under positive selection pressure in humans–, and its expression is deregulated in cancers, how TRIM52 expression is regulated has remained unexplored." (PMID 31133683, 2019). "RT-qPCR analysis had indicated that TRIM52 mRNA is expressed to similar, moderate levels in various commonly used human cancer cell lines (approximately eight RT-qPCR cycles above the detection limit; data not shown), suggesting it was feasible to expect detectable amounts of TRIM52 protein." (PMID 29568378, 2018). "However, a recent genome-wide ablation screening study has suggested that TRIM52 may be essential for optimal proliferation or survival in certain genetic cancer backgrounds." (PMID 29568378, 2018). "Although the exact molecular mechanism by which TRIM52 does so has remained elusive, this study shows that this evolutionary non-conserved protein could be a target for combinatorial gene disruption approaches in certain cancer types." (PMID 29568378, 2018). "Activation of the NF-κB pathway is also positively correlated with TRIM52, TRIM14, and TRIM31 and promotes cancer development in cancers." (PMID 36261847, 2022). "Together, our findings point to a non-redundant TRIM52 function that is required for optimal proliferation in certain cancer cell lines." (PMID 29568378, 2018). "Yet, in contrast, recent analysis of several genome-wide ablation screening studies has suggested that TRIM52 may be essential for optimal proliferation or survival of some cancer cell lines, but not others." (PMID 29568378, 2018). "Moreover, the observed cell fitness phenotype was not fully penetrant for any particular cancer- or tissue-type, suggesting that rather the cell-specific genetic make-up determines whether TRIM52 targeting confers a decrease in fitness." (PMID 29568378, 2018).